TTR (transthyretin)
Diseases named in the same sentence as TTR in open-access papers (continued):
Sharing a sentence is not in itself a finding about the gene and the disease.
Alzheimer disease (98 papers, 2005 to 2026). A progressive, neurodegenerative disease characterized by loss of function and death of nerve cells in several areas of the brain leading to loss of cognitive function such as memory and language. "The amyloid beta peptide is associated with Alzheimer’s disease (AD), and sequestration of this amyloid biomarker by TTR has a well-established role in neuroprotection in AD." (PMID 38398647, 2024). "Aβ, which is the major causative protein of Alzheimer’s disease, and TTR have also been analyzed molecularly." (PMID 35402512, 2022). "Recognizing its neuroprotective role in Alzheimer’s disease, it seems paradox that TTR can both prevent and cause dementia." (PMID 34719408, 2021). "We described a novel network in CAVD that associates to Alzheimer’s disease in the interaction analysis and demonstrated the presence of TTR-enriched amyloid-like deposits in calcified aortic valves." (PMID 32987857, 2020). "With regard to Alzheimer’s disease and dementia, a decrease in transthyretin is correlated with increased risk of severe dementia." (PMID 31119189, 2019). "Recently, the ratio of native to cysteinylated TTR in cerebrospinal fluid has been suggested as a useful diagnostic tool for Alzheimer’s disease." (PMID 19662213, 2007). "Of note, both transthyretin and mir-204 have been implicated in regulating cell survival and may be involved in pathological states, such as Alzheimer’s disease and/or Schizophrenia." (PMID 33828466, 2021). "We have also identified and validated Alzheimer’s disease specific markers ectonucleotide pyrophosphatase/phosphodiesterase 2, lysosome-associated membrane protein 1, pro-orexin and transthyretin that have the potential to discriminate Lewy body dementia from Alzheimer’s disease." (PMID 26627638, 2015). "It is speculated that TTR modification may well be the mechanism underlying the morphological manifestation of amyloidose or Alzheimer’s diseases in patients surviving multiple trauma." (PMID 19662213, 2007). "Moreover, TTR has been associated with diseases such as Alzheimer disease and type 2 diabetes." (PMID 18334949, 2008). "Transthyretin (TTR) has gained attention due to its implication in Alzheimer's Disease (AD) by modulating amyloid-beta (Aβ) pathology." (PMID 41820479, 2026). "Recent research has highlighted the potential neuroprotective functions of TTR in the setting of Alzheimer’s disease (AD), which is the most common form of dementia and is caused by the deposition of amyloid beta (Aβ) and the resulting cytotoxic effects." (PMID 39192044, 2025). "Protein misfolding results in a plethora of known diseasessuchas Alzheimer’s disease, Parkinson’s disease, Huntington’sdisease, transthyretin-related amyloidosis, type 2 diabetes, Lewybody dementia, and spongiform encephalopathy." (PMID 37305264, 2023). "In other words, TTR can bind to Aβ and inhibit Aβ aggregation and toxicity, suggesting a protecting role for TTR in Alzheimer’s disease." (PMID 35402512, 2022). "Correlation between plasma transthyretin level and severity and progression of Alzheimer’s disease has also been reported." (PMID 33451315, 2021). "Transthyretin (TTR), a 55 kDa evolutionarily conserved protein, presents altered levels in several conditions, including malnutrition, inflammation, diabetes, and Alzheimer’s Disease." (PMID 34199897, 2021). "Taken together, these observations implicate the intriguing potential of TTR and TTR stabilizers as novel targets for therapeutic intervention in Alzheimer’s disease." (PMID 33800546, 2021). "TTR has neuroprotective functions and/or is a stress response factor in various adverse conditions, including ischemia, Alzheimer’s disease (AD), Crohn’s disease, osteoarthritis, and preeclampsia." (PMID 34359938, 2021). "Several studies reported the neuroprotective role of transthyretin in Alzheimer’s disease and in cases of cobalt-induced seizures in animals." (PMID 34803604, 2021).
Alzheimer disease (continued). "In several studies on Alzheimer’s disease (AD), CSF TTR levels were shown to be reduced, however, this does not seem to be specific for AD nor consistently reproduced by other studies." (PMID 34719408, 2021). "In favor of neuroprotection, it was shown that overexpression of wild-type tetrameric TTR in an APP23 transgenic mouse model of Alzheimer’s disease improved cognitive functions." (PMID 33256250, 2020). "TTR is also acknowledged for its neuroprotective role in the central nervous system (CNS), such as in Alzheimer’s disease (AD), a form of localized amyloidosis affecting the brain, and the most common form of dementia." (PMID 32197355, 2020). "In this review, we cover knowledge on novel TTR functions and the cellular pathways involved, spanning from neuroprotection to vascular events, while emphasizing its involvement in Alzheimer’s disease (AD)." (PMID 32197355, 2020). "The involvement of TTR against Aβ aggregation and toxicity in the context of Alzheimer’s disease is now well established and future efforts to exploit the role of TTR as therapeutic tool are expected." (PMID 32197355, 2020). "Attention has been given to TTR as a neuroprotective protein, in particular in Alzheimer ́s disease and stroke through its putative upregulation in the brain." (PMID 31479465, 2019). "TTR expression has also been found in the frontal cortex of postmortem brain tissues from patients with Alzheimer ́s disease." (PMID 31479465, 2019). "In the context of Alzheimer ́s disease, TTR has been suggested as a biological sequester of Aβ, since it is able to bind to soluble Aβ peptide, preventing the formation of amyloid fibers." (PMID 31479465, 2019). "For instance, it has been well reported that, similar to beta-amyloid in Alzheimer’s disease and α-Synuclein in Parkinson’s disease, TTR amyloidogenesis is also influenced by environmental or physiological factors, such as post-translational modifications." (PMID 31835306, 2019). "Some studies in rat and mouse models of Alzheimer ́s disease show an overexpression and production of mRNA transcription of TTR in the hippocampus." (PMID 31479465, 2019). "The neuroprotective role of TTR is extended to other pathologies besides Alzheimer’s disease (AD); in cerebral ischemia, CSF TTR enhances survival of endangered neurons, and, under nerve injury conditions, TTR improves nerve regeneration." (PMID 25084758, 2015). "In both healthy elderly and Alzheimer's disease patients, the CP functions normally to transport AA and folates actively from blood into CSF, synthesize and secrete transthyretin into CSF, and maintain CSF acid-base balance and ion concentrations." (PMID 24059870, 2013). "Lowered blood and cerebrospinal fluid (CSF) levels of transthyretin (TTR) - a clearance protein mainly produced in the liver and, autonomously, in the choroid plexus - are associated with Abeta accumulation in Alzheimer’s disease." (PMID 23133543, 2012). "In cerebrospinal fluid, TTR levels are raised and lowered in Parkinson's and Alzheimer's diseases respectively." (PMID 21470419, 2011). "TTR has been suggested as an A-Beta carrier and attempts to relate TTR levels and Alzheimer's disease have been made." (PMID 18682830, 2008). "A recently published study reported on differential post-translational modifications of TTR in Alzheimer’s disease." (PMID 19662213, 2007). "In several disease states, including diabetes, Alzheimer’s disease, Lewy body dementia, cerebrovascular disease, and osteoporosis, higher TTR levels may be protective." (PMID 40717228, 2025). "Furthermore, transthyretin has a neuroprotective effect in Alzheimer’s disease, and the plasma levels of this protein can be used as a biomarker for osteoporosis in elderly subjects." (PMID 35407122, 2022). "Moreover, TTR stability and/or its levels are reduced in type 1 diabetes and in Alzheimer’s Disease." (PMID 34199897, 2021).
Alzheimer disease (continued). "However, transthyretin showed ability to bind to beta amyloid attenuating beta amyloid aggregation, which has beneficial consequences against Alzheimer’s disease." (PMID 34500744, 2021). "In fact, TTR is also known as a neuroprotective protein in Alzheimer’s disease (AD)." (PMID 32998442, 2020). "Besides its well-known role in the transport of THs and vitamin A, TTR is increasingly recognized as possessing neuroprotective properties in multiple contexts, including cerebral ischemia and Alzheimer’s disease (AD)." (PMID 33212973, 2020). "Hence, further studies need to clarify if TTR is upregulated in the hippocampus and cerebellum or if it cannot been found in the cerebral cortex, hippocampus and cerebellum in models of Alzheimer ́s disease." (PMID 31479465, 2019). "Previous studies have reported that TTR also binds to amyloid β peptide (Aβ) and thus may play a role in Aβ clearance in Alzheimer’s disease brain." (PMID 30615651, 2019). "Recent evidence seems to suggest a neuroprotective role of TTR in Alzheimer’s disease." (PMID 31835306, 2019). "Based on the possibility that specific pathologies may induce the expression of TTR in different brain regions, some in vitro and in vivo studies have been conducted to assess a potential neuroprotective role of TTR in brain ischemia and Alzheimer ́s disease." (PMID 31479465, 2019). "In vitro studies also support TTR synthesis in neurons as neuroprotective in Alzheimer ́s disease, since primary cultures of mixed cortical and hippocampal neurons from APP23 mice express TTR, and there is an upregulation of ttr in the SH-SY5Y neuroblastoma cell line over-expressing APP695 isoform." (PMID 31479465, 2019). "TTR interacts with the β-amyloid peptide (Aβ) oligomers and fibrils and may play a neuroprotective role in Alzheimer's disease." (PMID 30615651, 2019). "Moreover, TTR synthesis by neurons from cortex and hippocampus has been interpreted as a natural neuroprotective response in Alzheimer ́s disease." (PMID 31479465, 2019). "The ability of TTR to fragment the Alzheimer’s disease-related beta-amyloid peptide recently has been reported to be central to its ability to decrease the toxicity of this peptide, and TTR also participates in the transport of beta-amyloid out of the brain to the liver." (PMID 30111340, 2018). "Interestingly, TTR also interacts with amyloid-β (Aβ) and plays a protective role in Alzheimer’s disease (AD) by sequestering Aβ and reducing proteopathic stress." (PMID 30213975, 2018). "In addition, TTR is also important in some brain diseases such as Alzheimer disease, schizophrenia, and depression." (PMID 30034649, 2018). "Alzheimer's disease related activities of Transthyretin and BRICHOS—containing proteins." (PMID 28360830, 2017). "By preventing the formation of amyloid beta fibrils, TTR may also play a neuroprotective role in degenerative diseases such as Alzheimer disease." (PMID 23593219, 2013). "We applied this method to investigatethe interaction between transthyretin (TTR) and the amyloid beta (Aβ)peptide, a system of interest due to transthyretin’s proposedrole in the clearance of Aβ peptide, whose accumulation in thebrain is associated with Alzheimer’s disease." (PMID 41573340, 2025). "In this model, increased levels of TTR were associated with the absence of Alzheimer’s disease." (PMID 41226753, 2025). "Thus, the targeting of Aβ degradation and Aβ aggregation inhibition in the brain via EVs and TTR could represent a new therapeutic candidate for Alzheimer’s disease." (PMID 35402512, 2022). "In addition to apoA-I, TTR is also involved on the cleavage of both neuropeptide Y (NPY) and Aβ peptide, suggesting an important role of TTR-mediated proteolysis either in physiologic or pathologic conditions, with major impacts on the biology of nervous system and Alzheimer's disease, respectively." (PMID 33362465, 2020).
Alzheimer disease (continued). "Moreover, TTR is an interesting therapeutic target for neurodegenerative diseases due to its recognized neuroprotective properties in the cognitive impairment context and interestingly in Alzheimer’s disease (AD)." (PMID 33212973, 2020). "In particular in Alzheimer ́s disease, TTR may have the capacity to sequester amyloid beta (Aβ)." (PMID 31479465, 2019). "Although prior findings appeared to support the hypothesis that nicotine may act through transthyretin to beneficially modify Alzheimer’s disease pathology, findings from the current study suggest that any beneficial effects of transthyretin would be limited to regions in close proximity to the d3V." (PMID 31119189, 2019). "Indeed, deterioration of CPECs has been hypothesized to contribute to the progression of these diseases, with a particular emphasis on the potential role of TTR in the removal of β-amyloid in Alzheimer’s disease." (PMID 30111340, 2018). "Since the mid-1990's a trickle of publications from scattered independent laboratories have presented data suggesting that the systemic amyloid precursor transthyretin (TTR) could interact with the amyloidogenic β-amyloid (Aβ) peptide of Alzheimer's disease (AD)." (PMID 22112803, 2011). "We have previously shown that treatment of Alzheimer’s Disease (AD) model mice with iododiflunisal (IDIF), a TTR tetramer stabilizing compound, prevents AD pathologies." (PMID 31541162, 2019). "Among the genes being down-regulated in the brains of Eya3 mutants, several are reported to be down-regulated also in Alzheimer's disease, e.g. ARPP19, BIRC4, MT3, SYT1 or TTR." (PMID 19102749, 2008). "Previous works on Alzheimer’s Disease/TTR (AD/TTR) mice models have also shown that the TTR-KO animals did not always follow the expected trend compared to the heterozygous models." (PMID 34199897, 2021). "Since TTR stability is vital in beta-amyloid clearance, CAB could also be relevant in Alzheimer’s disease therapy." (PMID 30934952, 2019). "Furthermore, administration of resveratrol to Alzheimer’s disease (AD) mice revealed an increase in TTR levels in plasma that does not result from higher expression of the protein, but, instead, might be related with increased TTR stability and longer half-life in circulation." (PMID 30875761, 2019). "Transthyretin (TTR), a homotetrameric protein that transports thyroxine and retinol both in plasma and in cerebrospinal (CSF) fluid provides a natural protective response against Alzheimer’s disease (AD), modulates amyloid-β (Aβ) deposition by direct interaction and co-localizes with Aβ in plaques." (PMID 30213975, 2018). "Second, the role of non-canonical proteins (e.g., transthyretin, DISC1) in proteinjury warrants exploration, particularly in non-Alzheimer’s dementias." (PMID 40463840, 2025).
neuropathy (88 papers, 2012 to 2026). A disorder affecting the nervous system that manifests with pain, tingling, numbness, and/or muscle weakness. "Due to progressive neuropathy, genetic testing for ATTRv was performed and identified a pathogenic variant in the TTR gene." (PMID 39917777, 2025). "Because of systematic screening, 145 patients affected by neuropathy underwent genetic testing, which were positive for mutations in the TTR gene in 14 cases (10%)." (PMID 37725003, 2024). "Hereditary transthyretin-mediated amyloidosis (ATTRv, v for variant) is a progressive disease caused by mutations in the TTR gene, leading to sensory-motor, axonal and length-dependent neuropathy." (PMID 37870643, 2024). "In the Swedish population, amyloid fibril composition determines the phenotype; ATTR consisting of full-length TTR is associated with early onset and neuropathy, whereas a mixture of TTR fragments is associated with late onset, neuropathy, and cardiomyopathy." (PMID 31907599, 2021). "Nevertheless, numerous TTR variants other than V30M have been identified and associated with highly variable age of onset, severity and progression rates of the neuropathy and cardiopathy." (PMID 31502419, 2019). "Planté-Bordeneuve and colleagues reported the effect of tafamidis in 43 TTR-FAP-treated patients with a variety of mutations (53% non-V30M TTR) at different stages of neuropathy followed long term." (PMID 31407119, 2019). "The TTR variant segregates into all branches in which offspring reported neuropathy in deceased parents, whereas the segregation of the MGA variant cannot fully explain the parental phenotypes." (PMID 27212199, 2016). "Ruberg FL et Berk JL suggested that neuropathy or conduction disturbances caused by the toxic effects of pre-fibrillar transthyretin aggregates may occur before significant amyloid deposition." (PMID 40422943, 2025). "Both were approved by the FDA for the treatment of ATTRv-associated neuropathy in 2018 after two randomized controlled trials (RCTs) demonstrated benefit in reducing circulating levels of TTR and neuropathy impairment and improving quality of life compared to placebo." (PMID 38720335, 2024). "The altered structure of TTR due to genetic mutations or its deposits due to aggregation could cause several deadly diseases such as cardiomyopathy and neuropathy in autonomic, motor, and sensory systems." (PMID 31216785, 2019). "Both drugs have shown therapeutic efficacy in all domains of neuropathy, whether somatic or autonomic, as well in quality of life, being consistent in all groups and TTR mutations." (PMID 31399774, 2019). "Advances in molecular genetics have identified key causative genes, including PMP22, MPZ, MFN2, TTR, EGR2, and CX32 (GJB1), which are implicated in Charcot–Marie–Tooth disease, Dejerine–Sottas syndrome, and related neuropathies." (PMID 41595476, 2026). "At week 65/66, ATTRv-PN patients treated once-monthly with eplontersen demonstrated a 70% reduction in serum TTR compared to placebo and a significant slowing of neuropathy progression, with −24.8 points difference to placebo in mNIS+7." (PMID 40649158, 2025). "Patisiran, in the APOLLO trial (n= 225), significantly improved neuropathy, autonomic symptoms, and cardiacbiomarkers in a cardiac subgroup, with sustained TTR knockdown and favorabletolerability." (PMID 41524050, 2025). "Overall, siRNA‐based agents targeting TTR production effectively halt neuropathy progression and maintain functional capacity in patients with ATTR‐related neurological and cardiac involvement." (PMID 39576264, 2025). "NEURO-TTRansform was a clinical trial that enrolled patientswith hereditary ATTR amyloidosis polyneuropathy and demonstrated a significantdecrease in serum TTR concentration, neuropathy symptoms and better quality oflife compared to placebo." (PMID 41524065, 2025).